IL1B (interleukin 1 beta)
Diseases named in the same sentence as IL1B in open-access papers (continued):
Sharing a sentence is not in itself a finding about the gene and the disease.
dry eye (continued). "Five inflammatory cytokines IL-1β, TNF-α, IL-6, IL-8, and IFN-γ, were examined and compared between subjects with and without dry eye." (PMID 34957146, 2021). "In this study, fluorometholone showed significant inhibition of IL-1β and TNF-α expression of ocular surface epithelia and improvement of corneal fluorescein staining in the BTX-B dry eye mouse model, but did not change the tear production." (PMID 22815633, 2012).
prostatitis (78 papers, 2010 to 2025). An infectious or non-infectious inflammatory process affecting the prostate gland. "Prednisolone downregulates key pro‐inflammatory cytokines such as TNF‐α, IL‐1β, and IL‐6, which are implicated in the pathogenesis of both UC and chronic prostatitis." (PMID 40909304, 2025). "Genotype and allele frequencies of TNFA-308G/A and IL1B-31C/T in recurrent tonsillitis and control patients." (PMID 28542534, 2017). "We found an association between the presence of the IL1B-31*C allele (both homozygote plus heterozygote) and the development of recurrent tonsillitis." (PMID 28542534, 2017). "Patients with at least one copy of the IL1B-31*C allele had a higher risk of recurrent tonsillitis (OR = 4.03; 95% CI = 1.27–14.27; P = 0.013)." (PMID 28542534, 2017). "Several primary renal diseases and systemic diseases affecting the kidney are associated with NLRP3 inflammasome/IL-1β/IL-18 axis activation." (PMID 24450291, 2014). "In the process of kidney injury, M1 macrophages promote inflammation and tubular cell apoptosis by secreting pathogenic factors such as IL-1β, TNF-α and IL-6; however, M2 macrophages reduce inflammation and promote renal recovery by secreting trophic factors such as IL-10, TGF-β and arginase-1." (PMID 38785317, 2024). "Other genetic models include overexpression of the pro-inflammatory cytokines IL-1β or IL-6 in transgenic mice, and the Aire-deficient mouse model, in which knockout of the important immune regulator Aire led to development of chronic prostatitis." (PMID 35865005, 2022). "In conclusion, our results suggest that the presence of IL1B -31*C allele may be a tonsillitis-enhancing factor, especially when species such as S. aureus or H. influenzae are present." (PMID 28542534, 2017). "Chronic overexpression of Il1b in brain areas such as the hippocampus have been implicated in impaired spatial memory and in contextual fear memory in conditional transgenic mice, and with seizure susceptibility in animal models of sleep fragmentation and prostatitis." (PMID 35061107, 2023). "Thus, the presence of IL1B-31*C allele plus the presence of S. aureus and/or H. influenzae could be related to the development of tonsillitis in this particular Mexican population." (PMID 28542534, 2017). "Therefore, to elucidate the association among prostate epithelial cell pyroptosis, IL-1β, IL-17A, and IL-18 production, as well as Th17 differentiation, could be helpful in understanding the pathogenesis of chronic prostatitis and identifying therapeutic targets." (PMID 38993566, 2024). "Kidney inflammation indices (IL-1β, IL-6 and P-STAT3) were significantly decreased in CKD-DTBN as compared to CKD mice." (PMID 38555397, 2024). "When tubular epithelial cells were stimulated with several inflammatory cytokines, including TNF‐α, interleukin (IL)-1β, and IL-6, EMT was facilitated in the development of allograft kidney IF; however, the underlying mechanisms remained ambiguous." (PMID 37507403, 2023). "Previous studies found that the activation of the PI3K/Akt signaling pathway during liver ischemia-reperfusion injury, increased IL-4, and IL-10 expressions, decreased IL-1β and TNF-α expressions, and reduced the hepatic inflammatory response." (PMID 36835571, 2023). "The inflammasome responds to these signals triggering the release of mature IL-1β, which ligates the IL-1R receptor in the kidney cells, implicating the crucial role of inflammasome-IL-1β-IL-1R complex in kidney inflammation and progression to kidney failure." (PMID 36552226, 2022). "Among them, IL-1β is widely increased in CP/CPPS patients and animal models; IL-1β is not only an important inflammatory factor to maintain prostatitis but also one of the main reasons for the maintenance of tissue inflammatory immune cell infiltration." (PMID 34563249, 2021). "Markers of kidney inflammation, such as TNFα, IL1β, IL10, F4/80, MCP-1, and CRP, were assessed in total kidney tissues, isolated from both APN-KO and control mice." (PMID 33904399, 2021).
prostatitis (continued). "Here we got similar results as a recent study that hippocampal and serum levels of TNF-α, IL-1β, IL-6 were elevated accompanied by a drop in IL-10 level 24 h after middle cerebral artery occlusion in rats." (PMID 32848589, 2020). "Levels of IL-1β, IL-2 and IL-6 showed a significant increase in the recurrent tonsillitis group when compared to the hypertrophy group." (PMID 30213594, 2020). "Previous reports have found that the levels of some molecules associated with pain conditions, including CCL3, IL-1B, TNF-α, brain-derived neurotrophic factor (BDNF), and substance P, are increased in the spinal cord of prostatitis animal models." (PMID 31653262, 2019). "In summary, in this study, we established a key in vivo role for IL-1β in lung IR inflammation through the activity of the NLRP3 inflammasome." (PMID 29163464, 2017). "To further confirm the importance of IL-1β in lung IR inflammation, we used genetic and pharmacologic tools that target inflammatory caspases so as to disrupt the processing of IL-1β into its active form." (PMID 29163464, 2017). "Concomitantly, CRF rats treated with 200 IU rHuEPO also presented significantly higher values in protein and/or gene expression of several mediators of kidney inflammation and fibrosis, namely, Cyt C, IL-1β, and CTGF." (PMID 26712750, 2015). "P2X7R-NLRP3 axis could induce prostate epithelial cell pyroptosis by converting GSDMD to GSDMD-NT, which formed cell membrane pores and permitted IL-1β and IL-18 production and leakage to promote chronic prostatitis development." (PMID 38993566, 2024). "In addition, IL-1β is elevated in patients with chronic prostatitis, chronic pelvic pain syndrome, and BPH." (PMID 35664747, 2022). "Moreover, in the genetic mouse prostatitis model where interleukin 1β (IL-1β) is overexpressed, increased expression of downstream cytokines were observed, along with formation of PIA-like lesions and high expression of the proliferation marker Ki67." (PMID 35865005, 2022). "Importantly, the group of mice that received IL-1β-rescued Th9 cells with in vivo anti-IL-9 blockade exhibited reduced levels of inflammation indicating that both lung eosinophilia and airway inflammation are IL-9-dependent." (PMID 36389679, 2022). "The results showed that the content of propionic acid was negatively correlated with liver lipid accumulation (hepatic TG) and liver inflammation indexes (TNF-α, IL-1β and IL-6), while the content of butyric acid was negatively correlated with liver inflammation." (PMID 35052765, 2021). "Based on this model, we found that the NMT capsule could treat chronic prostatitis by mitigating the infiltration of inflammatory cells and reducing IL-1β and MDA levels in the prostate tissues." (PMID 32595732, 2020). "However, the CR kidney transplant patients had significantly elevated levels of proinflammatory cytokines IL-2 (P = 0.005), IL-1β (P = 0.05), and IL-6 (P = 0.05)." (PMID 24741575, 2014). "The levels of IL-1β, IL-6, and TNF-α were measured to investigate the impact of SP nutritional intervention on liver inflammation in ALD mice." (PMID 40362898, 2025). "Increasing reports have demonstrated that suppressing the production of pro-inflammatory cytokines, such as IL-1β, IL-6, and TNF-α, can reduce the effect of prostatitis." (PMID 39291282, 2024). "In this study, CC inhibited the increased expression of MCP-1, IL-6, IL-1β, COX-2, ICAM-1, and F4/80 in AD-induced kidney injury." (PMID 37513959, 2023). "Elevated levels of IL-18, S100A8/A9 specifically in serum and IL-1β in saliva can be used as a novel, objective biomarkers and collectively scored using the RAT-score to identify patients with recurrent tonsillitis." (PMID 34187480, 2021). "Effects of liver IR combined with intraperitoneal administration of aucubin (1, 5, and 10 mg/kg for 10 days) on serum TNF-α, IL-1β, and HMGB1 levels in experimental rats." (PMID 33013386, 2020).
prostatitis (continued). "Khalili M etal found a significant decrease in AR expression in infected prostate glands by preparing a bacterial prostatitis model, and very low TNF-α and IL-1β exposure can also lead to inhibition of the androgen receptor pathway." (PMID 31372097, 2019). "IL-1β and TNF-α are both pro-inflammatory cytokines and reported to be up-regulated in prostatic sections of prostatitis, suggesting that these are the key markers in inflammatory prostate." (PMID 31646996, 2019). "Seminal plasma from patients with chronic prostatitis (CP)/chronic pelvic pain syndrome show significantly higher levels of TNF-α and IL-1β when compared with those from healthy subjects, while no involvement of IFN-γ has been reported." (PMID 29896191, 2018). "Upon analysis, expression of the cytokines IFNB1, IFNG (IFN-γ), TNF (TNF-α), TGFB1 (TGF-β), IL1B, IL2, IL6, CXCL8 (IL-8), and IL10 were all significantly increased in ‘mesenchymal’ lung ADC compared to ‘epithelial’ tumors." (PMID 29440769, 2018). "In a lipopolysaccharide-induced acute lung injury model, dexmedetomidine improved congestion and edema and reduced the w/d weight ratio and TNF-α, IL-1β and IL-6 levels in lung tissues." (PMID 24345905, 2014). "In a left coronary artery ligation-induced I/R injury model, oral administration of quercetin at 2, 10, or 20 mg/kg for five consecutive days significantly reduced serum and myocardial levels of TNF-α, IL-6, and IL-1β." (PMID 40672380, 2025). "It is reported that total glucosides of V. officinalis attenuate chronic nonbacterial prostatitis in rat models by reducing the release of IL-2, IL-1β, and TNF-α in the prostate." (PMID 37108306, 2023). "They rarely observed IL1β and TNF-α in the recurrent tonsillitis group." (PMID 30213594, 2020). "Our study indicates that lung IR inflammation is mediated by the NLRP3 inflammasome and IL-1β and may have beneficial effects to the host in the context of superimposed bacterial lung infection." (PMID 29163464, 2017). "Although IL-1α showed strong cytoplasmic expression, especially in dilated atrophic renal proximal tubule cells of DN patients, no IL-1β could be detected in any of the kidney DN samples." (PMID 32733443, 2020). "In addition to causing an increase in all of the indices of inflammation in the tissue, the ethanol-DNBS-induced prostatitis resulted in an elevation of the tissue proinflammatory cytokines IL-6, IL-1β, and KC but not TNF-α." (PMID 24459330, 2013). "Since increased levels of inflammatory cytokines including IL-1β and TNF-α are also found in prostatitis, with or without bacterial infection, they may also up regulate CFTR in the prostate, thereby enhancing HCO3− secretion and leading to the characteristic pH increase in prostatitis." (PMID 21151921, 2010).
acute pancreatitis (77 papers, 2005 to 2025). An acute inflammatory process that leads to necrosis of the pancreatic parenchyma. "Besides, in a mice model of acute pancreatitis, low-methoxyl PEC was found to downregulate TNF-α, IL-1β and IL-6 mRNA levels in ileal and colonic tissue, leading to the recovery of acute pancreatitis-associated disorder of the intestinal barrier." (PMID 32276396, 2020). "The regulatory role of NQO1 for the alleviation of acute pancreatitis by reducing serum IL-1β was also reported." (PMID 40825682, 2025). "ROS produced by acute pancreatitis stimulate NF-κB, leading to excessive release of cytokines such as interleukin-1β (IL-1β), interleukin-2 (IL-2), interleukin-18 (IL-18), interleukin-6 (IL-6), and TNF-α." (PMID 40411704, 2025). "The severity of pancreatic pathological injuries in acute pancreatitis correlates significantly with the levels of infiltrated inflammatory cell-mediated cytokines, such as IL-1β, IL-6, and tumor necrosis factor-alpha (TNF-α)." (PMID 38550755, 2024). "The TNF-α, IL-1β, and IL-10 increased significantly in rats of the pancreatitis group of this study compared to healthy rats, they are considered indicators for acute pancreatitis and this finding is consistent with the findings of other authors." (PMID 38333760, 2024). "Serum levels of interleukin (IL)‐1β, IL‐5, IL‐6, IL‐8, IL‐10, IL‐17, and tumor necrosis factor‐α were significantly higher in the severe acute pancreatitis (SAP) group than in the non‐SAP group (p < .05)." (PMID 38411379, 2024). "Within this subpopulation, we observed a significant upregulation and activation of genes and pathways related to inflammation, with IL1B showing a positive correlation with the severity of acute pancreatitis." (PMID 39372399, 2024). "Ali and Madkour suggested that the tissue concentrations of TNF-α, IL-6, and IL-1β in the melatonin pretreatment group were significantly lower than in the L-arginine-induced acute pancreatitis group." (PMID 38333760, 2024). "As supported by previous studies, genes like S100A12, S100A9 and IL-1B hold substantial value as markers for predicting the severity of Acute Pancreatitis, in line with our research results." (PMID 39372399, 2024). "Serum IL-1β, IL-6 and IL-10 concentrations have been shown to increase after 6 to 12 h of severe acute pancreatitis in pigs." (PMID 37175426, 2023). "Animal studies showed that inhibiting the activity of IL-1β benefited the severity and mortality of acute pancreatitis, whereas overexpression of IL-1β induced the development of chronic pancreatitis." (PMID 37781392, 2023). "It was shown that the level of Il-6 and Il-1β corresponds with the severity of acute pancreatitis and the overexpression of Il-1β in the murine induces chronic pancreatitis." (PMID 37371528, 2023). "Acute pancreatitis is also characterized by increases in pancreatic pro-inflammatory cytokines and chemokines, including IL-1β, IL-6, IL-8, and monocyte chemoattractant protein-1 (MCP-1) which drive inflammation and tissue damage." (PMID 37180135, 2023). "In the acute pancreatitis groups, serum amylase, IL-6, and IL-1b levels were statistically significantly raised compared to the sham group (P < .01)." (PMID 36262104, 2022). "Plasma amylase, IL-6, and IL-1β levels were significantly elevated in acute pancreatitis groups (p < 0.05)." (PMID 36945982, 2022). "Elevated levels of NLRP3, caspase-1 and IL-1β protein expression and IL-1β and IL-18 transcription were identified in l-arginine-induced severe acute pancreatitis (SAP), cisplatin and contrast agent related AKI mouse models." (PMID 36117692, 2022). "Plasma amylase, IL-6, and IL-1β levels in the groups with acute pancreatitis were significantly increased when compared to the sham group (p < 0.01)." (PMID 36945982, 2022). "It has been reported that the production of pro-inflammatory cytokines, including TNF-α, IL-1β and IL-6, is a vital player in the pathogenesis of acute pancreatitis." (PMID 35042436, 2022).
acute pancreatitis (continued). "Rau and collaborators observed that the immunosuppressant tacrolimus inhibited the infiltration of neutrophils in rats via reduction of the expression of the mRNA for TNF-α and IL-1β in a model of acute pancreatitis induced by taurocholate." (PMID 34206998, 2021). "In acute pancreatitis, C/EBP homologous protein (CHOP) is induced by ER stress and was linked to apoptosis by inflammasome activation and IL‐1β secretion." (PMID 34132031, 2021). "Macrophages are a major source of TNF‐α, IL‐1β, and IL‐6, and high serum levels of these cytokines are consistent with acute pancreatitis disease severity." (PMID 32638512, 2020). "A comprehensive systematic review and meta‐analysis of the genetic evidence for acute pancreatitis was conducted, and identified credible associations of SPINK1, ALDH2, IL1B, IL6 and IL18 with the risk of acute pancreatitis." (PMID 32011822, 2020). "Further, PEG35 ameliorated the inflammatory response induced by acute pancreatitis-derived exosomes by reducing the expression of IL1β and p65 nuclear translocation." (PMID 33353210, 2020). "In acute pancreatitis, pro-inflammatory cytokines such as Interleukin-1β (IL-1β), IL-6 and tumor necrosis factor-α (TNF-α) are primarily produced within the pancreas and subsequently within distant organs." (PMID 32471279, 2020). "In vivo, studies have shown that infiltrating inflammatory cells play a crucial role in experimentally induced acute pancreatitis through the production of inflammatory mediators such as IL-1β and MCP-131,32." (PMID 30584237, 2018). "TNFα is a key role in severe acute pancreatitis, triggers expression of other inflammatory cytokines such as IL-1β and aggravates the tissue injury." (PMID 28441432, 2017). "GHRL induced anti-inflammatory cytokine IL-4, which suppressed IL-1β expression in cerulein-induced acute pancreatitis." (PMID 29068376, 2017). "TNFα, playing a dominating role in severe acute pancreatitis, can trigger expression of other inflammatory cytokines such as IL-1β and IL-6 and aggravates the tissue injury." (PMID 28441432, 2017). "Blocking of IL-1β with specific antagonists decreases the severity of experimental acute pancreatitis, further supporting a role for IL-1β in mediating pancreatic injury." (PMID 26347203, 2015). "Inflammatory cytokines such as interleukin-1β (IL-1β) and interleukin-6 (IL-6) play key roles in acute pancreatitis at the early stage of HTAP." (PMID 25365448, 2014). "Peritoneal macrophages activation during acute pancreatitis was confirmed by the increased mRNA expression of TNFα and IL1β." (PMID 22870264, 2012). "Stimulation of production of either acute phase proteins and adhesion molecules or several inflammatory cytokines, including TNF-α, IL-1β and IL-6, occurs after NF-κB activation in acute pancreatitis." (PMID 15987389, 2005). "Similarly, paeonol inhibited the M1 macrophage polarization thereby reduced serum levels of amylase, lipase, IL-1β and IL-6 and alleviated the histopathological manifestations of pancreatic tissue in a mild acute pancreatitis model." (PMID 41145464, 2025). "Similarly, a study suggested that the levels of TNF-α, IL-1β, and IL-6 were increased in acute pancreatitis groups compared with the sham group." (PMID 38333760, 2024). "Also, it has been stated that proinflammatory cytokines (TNFα, IL-1β, and IL-6) were significantly reduced, whereas antiinflammatory cytokines (IL-10 and IL-4) were increased in animals with acute pancreatitis pretreated with melatonin." (PMID 38333760, 2024). "Curiously, as a result of Galunisertib treatment, a reduced serum levels of MPO, IL-1β and IL-6 were observed in the acute pancreatitis model, implying those factors could also contribute to mesenchymal activation." (PMID 38322992, 2024). "Studies suggested that calycosin could diminish the levels of TNF-α, IL-6, and IL1B in mice with acute pancreatitis." (PMID 35227280, 2022).